ZNG1C (Zn regulated GTPase metalloprotein activator 1C)
Description:
Zinc chaperone that directly transfers zinc cofactor to target metalloproteins, thereby activating them. Catalyzes zinc insertion into the active site of methionine aminopeptidase METAP1, which function to cleave the initiator methionine from polypeptides during or after protein translation. Mechanistically, the N-terminal psi-PxLVp motif binds to the C6H2-type zinc finger of inactive form of METAP1. After formation of the docked complex, zinc is transferred from the CXCC motif in the GTPase domain of ZNG1C to the zinc binding site in the peptidase domain of METAP1 in a process requiring GTP hydrolysis. GTP/GDP exchange is required for release of active METAP1.
Synonyms: CBWD3; bA561O23.1
Tractability: Antibody: the Human Protein Atlas places it where antibodies can reach. PROTAC: ubiquitination databases record sites on it.
Gene: Protein-coding gene on chromosome 9 (68,232,003 to 68,300,036, forward strand). Ensembl gene ENSG00000196873.
Subcellular location: Nucleus
Subcellular location (Human Protein Atlas): Plasma membrane
Gene Ontology:
Molecular function: protein binding; GTPase activity; zinc chaperone activity; zinc ion binding
Biological process: protein maturation
Cellular component: nucleus
Genetic constraint (gnomAD): Loss-of-function variants: 0 observed, 2.7 expected, observed/expected ratio (o/e) 0, 90% interval 0 to 1.08. That is too few expected variants to judge how well the gene tolerates losing a copy. Missense variants: 1 observed, 32.13 expected, observed/expected ratio (o/e) 0.0311, 90% interval 0.01 to 0.15. Synonymous variants: 1 observed, 12.97 expected, observed/expected ratio (o/e) 0.0771, 90% interval 0.026 to 0.37.
Homologues: Orthologues: macaque ZNG1 (98% identical), dog ZNG1 (90% identical), mouse Zng1 (81% identical), rat Zng1a (79% identical), tropical clawed frog zng1b (68% identical), zebrafish cbwd (66% identical). Paralogues in human: ZNG1E (99% identical), ZNG1F (99% identical), ZNG1A (98% identical), ZNG1B (98% identical).